SIRT6 (sirtuin 6)
Diseases named in the same sentence as SIRT6 in open-access papers (continued):
Sharing a sentence is not in itself a finding about the gene and the disease.
angina (3 papers, 2023 to 2025). "A recent research paper discovered that serum Sirt6 expression level in patients with stable angina or with acute coronary syndrome was much lower than that of normal patients." (PMID 37497437, 2023). "In addition, in patients with stable angina or acute coronary, decreased serum SIRT6 expression is observed." (PMID 39971710, 2025). "The nomogram for CAD outcome prediction in older adult patients with angina pectoris may aid in clinical trial design and personalized clinical decision-making, particularly in institutions where SIRT6 is being explored as a biomarker for aging or cardiovascular health." (PMID 39851250, 2025).
breast tumor (3 papers, 2019 to 2023). "On the other hand, in breast tumors with mutated PI3KCA, SIRT6 overexpression inhibits PI3K signaling in a deacetylase activity-independent fashion and thereby affects the cancer stem cell compartment." (PMID 33482921, 2021).
calcification (3 papers, 2025). Process by which organic tissue becomes hardened by the physiologic deposit of calcium salts. "SIRT6 was markedly downregulated in the radial artery tissue of patients with vascular calcification, and SIRT6‐transgenic (SIRT6‐Tg) mice showed alleviated vascular calcification." (PMID 41180381, 2025). "Activation of both SIRT1 and SIRT6 may become a promising clue for treatment of vascular calcification." (PMID 41353172, 2025). "Notably, SIRT1, SIRT2, SIRT3, SIRT6, and SIRT7 have demonstrated therapeutic potential in the treatment of vascular calcification." (PMID 41480421, 2025).
cardiac ischemia (3 papers, 2023 to 2024). "Through the incorporation of Sirt6 into exosomes, we believe that these engineered exosomes gained additional therapeutic properties, making them capable of improving myocardial ischemia–reperfusion injury." (PMID 38172884, 2024). "In conclusion, our study sheds light on the novel therapeutic potential of Sirt6-enriched exosomes derived from adipose stem cells (ASCs) against myocardial ischemia/reperfusion injury (MIRI)." (PMID 38172884, 2024). "However, overexpression of SIRT6 in ecSirt6−/−mice yielded improved cardiac functions after cardiac ischemia reperfusion." (PMID 37598403, 2023). "Furthermore, endothelial cell‐specific Sirt6 knockout (ecSirt6−/−) mice were subjected to cardiac ischemia‒reperfusion surgery to investigate the effects of SIRT6 in CMECs in vivo." (PMID 37598403, 2023).
cutaneous squamous cell carcinoma (3 papers, 2024 to 2025). "Based on this, the authors speculate that SIRT6 may be involved in the biological behavior of cutaneous squamous cell carcinoma cells as a functional molecule." (PMID 38548549, 2024).
esophageal cancer (3 papers, 2017 to 2025). A primary or metastatic malignant neoplasm involving the esophagus. "As a result, SIRT6-4KR promotes the proliferation of esophageal cancer cells compared to SIRT6 WT." (PMID 38954215, 2025). "Indeed, SIRT6 has been previously suggested to affect the autophagy in human bronchial epithelial cells and esophageal cancer cells." (PMID 29234488, 2017).
Infertility (3 papers, 2015 to 2021). "To investigate the mechanism underlying the infertility of Sirt6-/- mice, we first examined meiotic progression by immunostaining the axial components of the synaptonemal complex and γH2Ax." (PMID 32915773, 2020). "Overall, we found that Sirt6 global knockout resulted in infertility in male mice, and spermatogenesis in Sirt6-/- mice was arrested at the elongated spermatid stage." (PMID 32915773, 2020). "Also striking is the 6.5-fold reduction in Sirt6 because of the direct relationship of sirtuins with FOXO3A and infertility." (PMID 25658474, 2015).
intervertebral disc degeneration (3 papers, 2018 to 2025). "Taken together, our study highlights the contribution of SIRT6 in modulating DNA damage, autophagy, and cell senescence and its importance in maintaining disc health during aging, thereby underscoring it as a potential therapeutic target to treat intervertebral disc degeneration." (PMID 40335469, 2025).
intestinal cancer (3 papers, 2017 to 2022). "Here, we show that the histone deacetylase SIRT6 regulates tumor initiation during intestinal cancer by controlling glucose metabolism." (PMID 35314684, 2022).
kidney damage (3 papers, 2017 to 2025). "SIRT6 overexpression decreased the secretion of TNFα and IL-6, inhibited apoptosis induced by LPS, and promoted autophagy in HK-2 human kidney tubular epithelial cells, suggesting that the initial increase in SIRT6 levels might be connected to the repair of LPS-induced kidney damage." (PMID 38016059, 2023). "Podocyte-specific deletion of Sirt6 exacerbated podocyte injury and proteinuria in two independent mouse models including DN and adriamycin (ADR)-induced nephropathy." (PMID 28871079, 2017). "We first confirmed the reduction of Sirt6 in renal biopsies from DN (n = 8) and FSGS (n = 10) subjects compared with normal subjects or diabetic patients without nephropathy (DM-NN, n = 7) by immunohistochemistry (IHC) staining and real time reverse transcription (RT)-PCR analysis." (PMID 28871079, 2017).
lipid metabolism disorders (3 papers, 2021 to 2026). "The results indicated that SNF2H was indispensable to Sirt6 that play an important role in regulating lipid metabolic disorders and the formation of foam cells." (PMID 37736721, 2023). "Reconstitution of Sirt6 recruited using SNF2H suppressed Wnt1 expression and improved lipid metabolism disorder by promoting lipophagy." (PMID 37736721, 2023).
medulloblastoma (3 papers, 2021 to 2025). A malignant, invasive embryonal neoplasm arising from the cerebellum. "Taken together, RBM5-AS1 associates with and stabilizes SIRT6 protein in medulloblastoma cells." (PMID 34225779, 2021). "In vivo studies demonstrated that reducing RBM5-AS1 levels suppresses tumor growth and enhances radiosensitivity, while its overexpression lessens radiation-triggered apoptosis and DNA damage in medulloblastoma cells through sirtuin 6 (SIRT6)." (PMID 41149459, 2025). "Our data confirm the role of SIRT6 in the regulation of DNA damage response of medulloblastoma cells." (PMID 34225779, 2021). "Overexpression of SIRT6 rescued medulloblastoma cells from RBM5-AS1 depletion-induced radiosensitization and DNA damage." (PMID 34225779, 2021). "Similar to the phenotype of RBM5-AS1-depleted cells, depletion of SIRT6 reduced the stem-like properties and enhanced radiation-induced DNA damage in medulloblastoma cells." (PMID 34225779, 2021). "To investigate the importance of SIRT6 in RBM5-AS1-mediated aggressive phenotype, we knocked down SIRT6 in medulloblastoma cells." (PMID 34225779, 2021). "Nevertheless, SIRT6 mediates the oncogenic activity of RBM5-AS1 in medulloblastoma through promotion of stem-like capacity and attenuation of DNA damage." (PMID 34225779, 2021). "Silencing of SIRT6 reduced the stemness and reinforced radiation-induced DNA damage in medulloblastoma cells." (PMID 34225779, 2021). "Given the interaction between RBM5-AS1 and SIRT6, we asked whether RBM5-AS1 could modulate the expression of SIRT6 in medulloblastoma cells." (PMID 34225779, 2021). "Consistently, our data indicate that SIRT6 knockdown impairs the stemness of medulloblastoma cells." (PMID 34225779, 2021). "Specially, we discover that RBM5-AS1 interacts with SIRT6 protein in medulloblastoma cells." (PMID 34225779, 2021). "Thus, SIRT6 is functionally relevant to RBM5-AS1 in medulloblastoma." (PMID 34225779, 2021).
nasopharyngeal carcinoma (3 papers, 2021 to 2022). A carcinoma arising from the nasopharyngeal epithelium. "In nasopharyngeal carcinoma, SIRT6 overexpression reduces levels of anti-apoptotic protein Bcl-2 but increases levels of cleaved caspase-3 and pro-apoptotic protein Bax." (PMID 35463332, 2022). "High levels of SIRT6 inhibit NF-κB signaling and promote apoptosis of nasopharyngeal carcinoma cells." (PMID 35463332, 2022). "SIRT6 promoted the apoptosis of nasopharyngeal carcinoma cell lines as Bcl expression was decreased, accompanied by increased TUNEL-positive cells." (PMID 34927546, 2021).
nonalcoholic steatohepatitis (3 papers, 2022 to 2023). "SIRT6 protein levels are decreased and ACSL5 K361 acetylation levels are increased in the liver of nonalcoholic steatohepatitis (NASH) patients compared to those in healthy controls." (PMID 36831330, 2023).
premature aging syndrome (3 papers, 2012 to 2022). Changes in the organism associated with senescence, occurring at an accelerated rate. "Previous studies have indicated that SIRT6 inhibited the overactivation of primordial follicles and prolonged the ovarian function lifespan, while SIRT6-deficient-mice developed premature aging syndromes." (PMID 35927704, 2022).
prostate tumor (3 papers, 2018 to 2023). "A recent study found that SIRT6 was overexpressed in prostate tumors compared with normal or paratumor prostate tissues." (PMID 38136586, 2023).
psoriasis (3 papers, 2021 to 2024). An autoimmune condition characterized by red, well-delineated plaques with silvery scales that are usually on the extensor surfaces and scalp. "There is a significant reduction in the expression of SIRT1, SIRT2, SIRT3, SIRT4 and SIRT5 and an increase in the expression of SIRT6 and SIRT7 in psoriasis." (PMID 37445960, 2023). "Psoriasis shows reduced SIRT1-5 expression and increased SIRT6 and SIRT7 expression." (PMID 38892253, 2024). "Based on their activity, SIRT1–SIRT5 agonists and SIRT6 and SIRT7 inhibitors may represent new therapeutic options for the treatment of psoriasis, but more studies are needed to confirm this eventuality." (PMID 37445960, 2023). "In light of the analysis of the mode of action of SIRTs in psoriasis, SIRT1–SIRT5 agonists and SIRT6 and SIRT7 inhibitors may represent new therapeutic options for the treatment of psoriasis." (PMID 37445960, 2023). "The dysregulation of this auto-regulatory loop could be also due to the abnormal expression of SIRTs in psoriasis, with the downregulation of SIRT1, SIRT2, SIRT3, SIRT4, and SIRT5 and upregulation of SIRT6 and SIRT7 in skin lesions skin, as previously reported." (PMID 34202251, 2021).
pulpitis (3 papers, 2022 to 2023). Inflammation of the dental pulp. "Intriguingly, SIRT6 can also suppress inflammation induced by LPS in pulpitis through promoting the ubiquitination of the transient receptor potential vanilloid 1 (TRPV1) channel." (PMID 36060706, 2022). "A further study showed that overexpression of SIRT6 in HDPCs rescued apoptosis and impaired cell viability induced by LPS, suggesting a cell-protective effect of SIRT6 in pulpitis." (PMID 36060706, 2022). "Moreover, the overexpression of SIRT6 could inhibit pulpitis by activating the TRPV1 channel." (PMID 35249460, 2022).
skin squamous cell carcinoma (3 papers, 2020 to 2021). A carcinoma arising from the squamous cells of the epidermis. "It has been reported that SIRT6 has a role in the regulation of cyclooxygenase (COX)-2 mRNA stability by repressing AMP-activated protein kinase (AMPK) signaling pathway in human skin squamous cell carcinoma." (PMID 33718364, 2021).
Ureteral obstruction (3 papers, 2022 to 2023). Obstruction of the flow of urine through the ureter. "Previous study suggests that loss of SIRT6 aggravates unilateral ureteral obstruction-induced tubulointerstitial inflammation and fibrosis." (PMID 36172184, 2022). "This study investigates the effect of proximal tubule-specific Sirt6 knockdown on unilateral ureteral obstruction (UUO)-induced renal tubulointerstitial inflammation and fibrosis." (PMID 35563783, 2022). "Therefore, through immunofluorescence staining for α-SMA and FSP-1 expression after 7 d of ureteral obstruction, we investigated whether proximal tubule Sirt6 has a role in UUO-induced myofibroblast activation." (PMID 35563783, 2022).
adenovirus infection (2 papers, 2018 to 2021). "Interestingly, adenovirus infection with deacetylase‐mutant Sirt6 (Ad‐Sirt6H133Y) produced similar results with wild Sirt6, indicating that the deacetylase activity of Sirt6 is dispensable for regulating eosinophil differentiation." (PMID 34125994, 2021).
cerebrovascular diseases (2 papers, 2019 to 2022). "Although recent studies have focused on SIRT6 in cardiovascular disorders, the role of SIRT6 in aging-related cerebrovascular diseases is not fully understood." (PMID 35855341, 2022). "Both in vitro and in vivo studies demonstrated that SIRT6 produced beneficial effects in cerebrovascular diseases models." (PMID 30791908, 2019).
Cholestatic liver disease (2 papers, 2020 to 2024). "This regulatory mechanism is the key to the amelioration of cholestatic liver disease by SIRT6, as compared to the enhancement of antioxidant gene expression or the promotion of mitochondrial biogenesis." (PMID 39618181, 2024). "The present study demonstrates that SIRT6 acts as a protective factor against BDL-induced cholestatic liver disease." (PMID 39618181, 2024). "To further illustrate how SIRT6 functions in combating cholestatic liver disease, we used adenoviral vectors to overexpress SIRT6 in mouse liver, and subsequently carried out BDL." (PMID 39618181, 2024). "To investigate whether mitochondrial biogenesis affects SIRT6's resistance to cholestatic liver disease, we administered AICAR to liver-specific Sirt6 knockout mice to activate the AMPK/PGC-1α pathway, or used KNI-1 to activate NRF2." (PMID 39618181, 2024). "Additionally, the hepatic knockdown of Cyp7a1 further demonstrated that inhibiting hepatic bile acid synthesis might be the main pathway through which SIRT6 alleviates cholestatic liver disease." (PMID 39618181, 2024). "Therefore, Sirt6 might become a new gene target for the treatment of cholestatic liver disease." (PMID 32206298, 2020). "To investigate the role of mitochondrial biogenesis in SIRT6's resistance to cholestatic liver disease, we administered the AMPK agonist AICAR to Sirt6Δhep mice, and observed a significant restoration of the AMPK phosphorylation and PGC-1α protein levels that were impaired by Sirt6 deletion." (PMID 39618181, 2024). "Therefore, mitochondrial biogenesis may not be the main pathway through which SIRT6 mitigates cholestatic liver disease." (PMID 39618181, 2024). "Considering that neither oxidative stress nor mitochondrial biogenesis serves as a pathway for SIRT6 in combating cholestatic liver disease, we theorized that the inhibition of bile acid synthesis might be the key mechanism underlying SIRT6's therapeutic function." (PMID 39618181, 2024). "Therefore, we treated liver-specific Sirt6 knockout mice with N-acetylcysteine, KEAP1-NRF2-IN-1, or acadesine to alleviate oxidative stress and/or promote mitochondrial biogenesis after modeling cholestatic liver disease, but these measures did not significantly improve cholestatic symptoms." (PMID 39618181, 2024).
chronic obstructive pulmonary disease (2 papers, 2016 to 2023). A chronic and progressive lung disorder characterized by the loss of elasticity of the bronchial tree and the air sacs, destruction of the air sacs wall, thickening of the bronchial wall, and mucous accumulation in the bronchial tree. "The role of SIRT6 in autophagy was first investigated in the context of cellular senescence in chronic obstructive pulmonary disease (COPD)." (PMID 38016059, 2023). "Sirtuin-1 (SIRT1) and SIRT6, NAD+-dependent Class III protein deacetylases, are putative anti-aging enzymes, down-regulated in patients with chronic obstructive pulmonary disease (COPD), which is characterized by the accelerated ageing of the lung and associated with increased oxidative stress." (PMID 27767101, 2016).
COVID-19 (2 papers, 2021 to 2024). A disease caused by infection with severe acute respiratory syndrome coronavirus 2. "Significant interest has been directed toward activating Sirt6, a member of this family, due to its potential as a therapeutic target for various diseases, including COVID-19." (PMID 39512644, 2024). "Finally, the known mislocation of SIRT1 and SIRT6 throughout the genome and the decline of NAD+ during aging could be major factors causing age-dependent symptoms of COVID-19." (PMID 34710058, 2021).
depression (2 papers, 2022). "Sirtuin 6 (SIRT6) plays a key role in mood regulation, and knockdown of hippocampal SIRT6 can alleviate depression-like behaviors induced by CUMS in mice." (PMID 35496318, 2022). "Chronic treatment with FA inhibits SIRT6 expression and may suppress AKT/CRMP2 signaling, ameliorating CUMS-induced depression-like behaviors in mice." (PMID 35496318, 2022).
developmental delay (2 papers, 2021 to 2022). "SIRT6 deficiency leads to hyperacetylation of histones at the imprinting control region of developmental repressor H19, which results in severe prenatal developmental delay and death several hours after birth in SIRT6-deficient monkeys." (PMID 35463332, 2022). "Sirtuin 6 deficiency in nonhuman primates results in developmental delay, including delay in neuronal differentiation." (PMID 34867200, 2021).
diseases of the joint (2 papers, 2016 to 2023). "Further understanding of the gene regulatory programs mediated by Sirt6-Blimp1 axis may provide a novel molecular basis for therapeutic strategies against bone and joint diseases." (PMID 27189179, 2016). "Thus, targeted strategies that maintain or activate SIRT6 to promote the chondrocyte phenotype and maintain cartilage ECM integrity represent promising avenues for both post-traumatic and age-associated OA therapy as well as other diseases of the joint." (PMID 37550003, 2023).
endometrial cancer (2 papers, 2019 to 2021). Primary or metastatic malignant neoplasm involving the endometrium (mucous membrane that lines the endometrial cavity). "It is the limit of this study for the role of upstream signaling pathway of SIRT6 in the mechanism of action of Fluvastatin in endometrial cancer cells." (PMID 34927546, 2021). "SIRT6 repression of survivin has also been demonstrated in cells with lower expression of SIRT6 as those of the endometrial cancer." (PMID 31591350, 2019). "The present study firstly shows the anti-tumor potential of fluvastatin in endometrial cancer and reveals the role of SIRT6 in the mechanism of action of fluvastatin, providing a novel sight for the therapy of endometrial cancer and the study of mechanism of endometrial cancer." (PMID 34927546, 2021). "Additionally, there is a report also demonstrating increased expression of SIRT6 promotes apoptosis of endometrial cancer cells by survivin." (PMID 34927546, 2021). "Therefore, we further explore whether fluvastatin can activate the expression of SIRT6 and affect the proliferation, invasion, migration as well as apoptosis of endometrial cancer cells, which may shed light on the role of fluvastatin in EC and reveal its underlying mechanism." (PMID 34927546, 2021). "The expression of SIRT6 was shown to negatively affect the proliferation of AN3CA and KLE endometrial cancer cells." (PMID 31591350, 2019). "However, there is no significant data that could relate the SIRT6 expression with endometrial cancer type or prognostic." (PMID 31591350, 2019).